RIPK1 (receptor interacting serine/threonine kinase 1)
Diseases named in the same sentence as RIPK1 in open-access papers (continued):
Sharing a sentence is not in itself a finding about the gene and the disease.
melanoma (44 papers, 2013 to 2026). A malignant, usually aggressive tumor composed of atypical, neoplastic melanocytes. "RIPK1 is also involved in skin inflammation, and the activation of RIPK1 is reportedly correlated with many skin diseases, including melanoma, psoriasis, systemic lupus erythematosus, and hair loss." (PMID 40004031, 2025). "In melanoma cells with active melanogenesis, the use of melanin synthesis inhibitors to induce depigmentation could also restore the susceptibility of melanoma cells to RIPK1/RIPK3/MLKL-mediated necroptosis." (PMID 35359389, 2022). "In addition, higher expression of RIPK1 was found to be linked with the higher metastasis rates in melanoma and confers a worse prognosis in melanoma potentially due to NF-κß mediated stimulation of tumor cells proliferation." (PMID 36361505, 2022). "Thus, depleting CYLD in melanoma cells leads to an increase in RIPK1 associated with an increase in K63-related polyubiquitination of RIPK1." (PMID 35884430, 2022). "For ICB resistance, interferon-γ receptor (IFNGR) signalling drives RIPK1 overexpression in tumour cells; genetic ablation of RIPK1 enhances ICB sensitivity in murine melanoma and breast cancer models." (PMID 41334873, 2025). "Upregulation of RIPK1 in human melanoma cells after tunicamycin or thapsigargin treatment reduces the sensitivity of cancer cells to drug-mediated ER stress." (PMID 41334873, 2025). "The combined induction of apoptosis (such as through the use of BH3 mimetics) and necroptosis (such as through the use of RIPK1 inhibitors) has been shown to significantly enhance the mortality rate of melanoma cells." (PMID 40331942, 2025). "TAK1 blocks TNF-α-induced RIPK1 activation and apoptosis in melanoma and LPS-induced necroptosis in bone marrow-derived macrophages." (PMID 39044278, 2024). "In melanoma cells actively engaged in melanogenesis, the use of melanin synthesis inhibitors to induce depigmentation has shown to restore sensitivity to RIPK1/RIPK3/MLKL-mediated necroptosis." (PMID 38036577, 2023). "In melanoma cells with active melanogenesis, induction of depigmentation with a melanin synthesis inhibitor restores melanoma cell sensitivity to RIPK1/RIPK3/MLKL-mediated necroptosis." (PMID 35610275, 2022). "Another apoptosis and necroptosis initiator RIPK1 is reported to be the major target of a negative regulation by TAK1, and is directly associated with melanoma progression and metastasis." (PMID 35422482, 2022). "Further studies revealed that in amelanotic melanoma cells, PBPs-induced death is related to inducing the RIPK1/RIPK3/MLKL-mediated necroptosis." (PMID 35359389, 2022). "Consistently, the activation of RIPK1 and the degradation of c-FLIPL was also reduced by phosphatase dead D84N mutant and melanoma-associated G112E, H114Y, and G189R mutants." (PMID 36071040, 2022). "Immunoprecipitation of induced GFP-tagged Usp27xL (GFP-IP) confirmed the presence of Usp27x in complex with RIPK1 in WM1158 melanoma cells (the same was seen in 1205Lu cells overexpressing GFP-mUsp27xS, data not shown) independently of TNF treatment." (PMID 35044632, 2022). "The viability of melanoma cells depigmented with 10−3 M d-pen, 6 μg/mL KA, or 30 μg/mL KA increased after CV stimulation when the RIPK1, RIPK3, and MLKL kinases were inhibited." (PMID 34072104, 2021). "To the best of our knowledge, we are the first to demonstrate that CV extract can induce RIPK1/RIPK3/MLKL-mediated necroptosis in depigmented melanoma cells." (PMID 34072104, 2021). "In another study, however, pre-treatment of mice with necrostatin-1 or a novel RIPK1 inhibitor, PK68, significantly suppressed lung metastasis by melanoma cells, suggesting that further research is needed to clarify the role of RIPK1 in melanoma progression." (PMID 32340261, 2020). "It has also been reported that low level of RIPK1 in melanoma cells promoted induction of apoptosis, and RIPK1 regulated autophagy in melanoma cells upon ER stress." (PMID 32340261, 2020).
melanoma (continued). "We evaluated multiple mechanisms of cell death in melanoma cells, including apoptosis, autophagy, caspase-independent pathways, and the participation of the receptor-interacting serine/threonine-protein kinase 1 (RIPK1) cascade." (PMID 29899823, 2018). "Our study is also consistent with a recent study indicating RIPK1 being a driver for melanoma growth." (PMID 26959742, 2016). "MLKL and RIPK1 protein was present in most melanoma cell lines, nevus cells, and primary melanocytes." (PMID 26355347, 2015). "We report here that although cotreatment with HDAC and BRAF inhibitors activates the caspase cascade and the mitochondrial apoptotic signaling, it kills BRAFV600E melanoma cells predominantly by induction of necrosis in a RIPK1- and RIPK3-independent manner." (PMID 23744355, 2013). "Collectively, these results indicate that the combination of SAHA and PLX4720 induces necrosis of melanoma cells independently of RIPK1 and RIPK3." (PMID 23744355, 2013). "Notably, in cancer research, RIPK1 upregulation in melanoma cells under endoplasmic reticulum stress induces autophagic pathways to clear damaged organelles, enhancing cancer cell survival." (PMID 41334873, 2025). "Additionally, TBK1/IKKε knockouts of both melanoma cell lines exhibited increased RIPK1 S166 phosphorylation, indicating heightened RIPK1 activation within the TNFR1 complex compared to WT controls." (PMID 41315176, 2025). "This indicates that the role of RIPK1 in melanoma cells is complex." (PMID 40497999, 2025). "With respect to metastasis, considering programmed necrosis as an illustrative example, recent studies have revealed that dysregulation in the expression of necroptosis-associated proteins RIPK1 and RIPK3 triggers the generation of a cascade of pro-inflammatory signals within melanoma cells." (PMID 40331942, 2025). "Additionally, a novel RIPK1 inhibitor PK68 significantly suppresses lung metastasis of mouse melanoma cells." (PMID 40497999, 2025). "Inhibitors targeting RIPK1 activity could significantly repress metastasis of both lung carcinoma cells and melanoma cells in mice." (PMID 34977874, 2021). "As a matter of fact, aberrant expression of RIPK1 could lead to the development of multiple tumors, including liver cancer, pancreatic cancer, melanoma, and so on." (PMID 31216707, 2019). "Reactivation of the RIPK1/RIPK3/MLKL signalling platform by RIPK3 reconstitution can overcome necroptosis resistance in melanoma and therefore could be used as potential death-inducing targeted therapy against melanoma." (PMID 26355347, 2015). "Interestingly, the cytoplasmic RIPK3 serine/threonine kinase has also been implicated in necroptic cell death of melanomas, but not the related RIPK1 pathway." (PMID 29880902, 2018). "As RIPK1 has an important role in initiating programmed necrosis in many types of cells induced by a variety of stimuli, we examined whether it is involved in necrosis of melanoma cells induced by cotreatment with SAHA and PLX4720." (PMID 23744355, 2013). "Although RIPK1 and MLKL levels are homogeneous in most melanoma cell lines, the expression of RIPK3 is extremely low, which has been associated with the absence of necroptosis." (PMID 40710498, 2025). "Necroptosis, governed by the receptor-interacting protein kinase 1 (RIPK1)/RIPK3 mixed lineage kinase domain-like protein (MLKL) signaling axis, can synergize with immunotherapy to enhance anti-melanoma immune responses when activated." (PMID 40497999, 2025). "More recent analysis also revealed that CV-induced cell death of melanoma cells is regulated by receptor-interacting protein-1 (RIPK1) and ROS, and that this process is modified by melanin content in melanoma cells." (PMID 36902290, 2023). "Related to the mechanism of action, our results show that CV extract induce RIPK1/RIPK3/MLKL-dependent necroptosis, in the depigmented melanoma cells, which serves as an alternative mode of programmed cell death to eradicate apoptosis-resistant cancer cells." (PMID 34072104, 2021).
melanoma (continued). "We co-cultured CV-stimulated depigmented melanoma cells with selected kinases inhibitors: necrostatin-1 (Nec-1), GSK’872 and necrosufonamide (NSA), which specifically target RIPK1, RIPK3, and MLKL activity, respectively." (PMID 34072104, 2021). "Several previous studied in gallbladder carcinoma, melanoma, breast cancer, HCC, and CCA suggested that RIPK1 harbors pro-tumorigenic functions through different mechanisms including NF-κB, autophagy, and apoptosis activation." (PMID 33036630, 2020). "TAK1 inhibition sensitized melanoma cells to apoptosis induced by a combination of TNF-α and TRAIL, indicating that TAK1 regulated apoptosis-related role of RIPK1 in melanoma." (PMID 32340261, 2020). "In melanoma models, PK68 and RIPK1-IN-7 potently inhibit pulmonary metastasis." (PMID 41334873, 2025). "IGF1R, RIPK1, and PSEN2 are already known to contribute to vemurafenib resistance, suggesting that our new analysis method using v reliably identified hits whose ablation can sensitize melanoma to vemurafenib." (PMID 36829149, 2023). "RIPK1, RIPK3, and MLKL might have different necroptosis-(in)-dependent roles during melanoma development." (PMID 35422482, 2022). "RIPK1 is described as an oncogenic driver in melanoma due to its scaffold function independent of the kinase function, while RIPK3 expression apparently is suppressed by the BRAF and AXL oncogenes." (PMID 35422482, 2022). "Activation of the RIPK1-dependent cell death program in target cells by T cell–derived TNF accelerates murine cardiac allograft rejection and synergizes with anti-PD1 administration to destroy checkpoint blockade–resistant murine melanoma." (PMID 34752416, 2021). "Accordingly, both loss of RIPK3 in the tumor microenvironment and loss of the kinase activity in RIPK1 have been reported to reduce tumor nodules in the lung in murine B16.F10 primary melanoma tumors, which further implies that RIPK3 and RIPK1 are fundamental for cancer growth and metastasis." (PMID 33665167, 2020). "In our studies, melanomas surprisingly lacked the execution of RIPK1-dependent necroptosis, usually uncovered when caspase function is blocked." (PMID 26355347, 2015). "Although the exact mechanism by which the two classes of inhibitors interact to induce necrosis of BRAFV600E melanoma cells remains to be defined, a number of factors including RIPK1, RIPK3, and generation of ROS do not appear to have a major role." (PMID 23744355, 2013). "To investigate cellular death in the B16F10 mouse melanoma cell model and its correlation with the mechanism of RIPK1 downregulation rather than kinase inhibition, we employed various tool molecules, including LD4172, T2I, TNFα, Smac mimetic LCL161, and the pan-caspase inhibitor Z-VAD-FMK." (PMID 39681571, 2024). "Thus, our study demonstrates that the regulation of LUBAC-mediated M1-ubiquitination of RIPK1 and c-FLIPL by PP6 can serve as a checkpoint for TNFα-mediated cell death, which may provide a potential mechanism for promoting melanoma progression." (PMID 36071040, 2022). "In addition, inhibition of RIPK1 and loss of RIPK3 did not reduce lung metastasis in a mouse model of melanoma." (PMID 32340261, 2020). "To date, Z‐DNA binding protein 1 (ZBP1)‐, Absent in Melanoma (AIM)‐, receptor‐interacting serine/threonine‐protein kinase 1 (RIPK1)‐, and NLR family pyrin domain containing 12 (NLRP12)‐ PANoptosomes have been characterized at the molecular level." (PMID 41362050, 2026). "To date, four distinct PANoptosomes have been identified: Z-DNA-binding protein 1 (ZBP1), absent in melanoma 2 (AIM2), receptor-interacting protein kinase 1 (RIPK1), and nucleotide-binding leucine-rich repeat-containing receptor 12 (NLRP12) PANoptosomes." (PMID 40568592, 2025). "With the manipulation of upstream RIPK1 and the effector protein of MLKL in the necroptosis pathway, the relevance of necroptosis to melanoma progression and metastasis is not clear." (PMID 38336727, 2024).
melanoma (continued). "Then, we discovered that the inhibitors of RIPK1, RIPK3, and MLKL kinases diminished the intracellular ROS generation triggered by CV compounds in non-pigmented melanoma cells." (PMID 34072104, 2021). "The CV extract has been also reported to induce RIPK1/RIPK3/MLKL-mediated necroptosis in non-pigmented melanoma cells and depigmented (with suppressed melanogenesis) melanoma cells, since co-treatment of the cells with necroptosis inhibitors abrogated the CV-induced cell death." (PMID 36902290, 2023).
Sepsis (40 papers, 2014 to 2026). Sepsis is defined as life-threatening organ dysfunction caused by a dysregulated host response to infection. "Comparative analysis across diagnostic categories revealed that patients with sepsis exhibited significantly elevated levels of RIPK-1, IL-1β, and IL-18, along with reduced caspase-8 levels, relative to patients with SIRS or cardiac conditions." (PMID 40722817, 2025). "In sepsis, Escherichia coli-derived LPS activates RIPK1, RIPK3, and MLKL in intestinal epithelial cells, causing severe barrier disruption—an effect attenuated by RIPK1 inhibition using necrostatin-1 (Nec-1)." (PMID 41142308, 2025). "To address rAAV off‐target limitations, we utilized a conditional gene knockout approach to further clarify the essential role and pathogenic mechanism of RIPK1 in ATII cells during sepsis‐induced lung injury." (PMID 40953301, 2025). "Our ROC analysis revealed that RIPK-1 and IL-18 demonstrated good diagnostic accuracy for sepsis within 24 h of ICU admission—suggesting strong potential as early biomarkers of disease severity." (PMID 40722817, 2025). "Other transcripts upregulated in CD5L− peritoneal cells, including Osm, Il18bp, Ripk1, Nub1, Tlr2, Stat1, Irf1, Nfkb1, Pik3r5, or their coding proteins, were already associated with sepsis severity." (PMID 38750020, 2024). "In clinical research, there has been relatively little investigation into the association between RIPK1 and sepsis." (PMID 37090690, 2023). "A recent study revealed that pathogenic Yersinia, which causes fatal sepsis and gastritis in humans, induces the formation of a RIPK1-PANoptosome complex to regulate PANoptosis." (PMID 38129399, 2023). "Although adult patients in our cohort exhibited significantly higher RIPK-1 levels than pediatric patients, the distribution of this biomarker across diagnostic categories was remarkably consistent—decreasing progressively through sepsis, SIRS, cardiac cases, and healthy controls in both age groups." (PMID 40722817, 2025). "Therefore, RIPK1 inhibition may be another means of alleviating the cytokine storm associated with sepsis." (PMID 37090690, 2023). "CONCLUSION: TS demonstrates a protective effect against sepsis-induced acute lung injury (ALI) by inhibiting the expression of RIPK1." (PMID 42015326, 2026). "To further explore the role of RIPK1 kinase activity in the development of sepsis, we used Ripk1D138N/D138N mice, which harbor a kinase‐dead mutation, in the CLP model." (PMID 40953301, 2025). "Our experiments demonstrated that knockdown of Ripk1 in alveolar epithelial cells significantly mitigated sepsis‐induced lung pathology, including alveolar hemorrhage and inflammatory infiltrates." (PMID 40953301, 2025). "To investigate RIPK1 activation dynamics in sepsis‐induced lung injury, we employed a lethal cecal ligation and puncture (CLP) model in adult male mice, in which survival is limited to a maximum of 72 h." (PMID 40953301, 2025). "Although receptor‐interacting serine/threonine‐protein kinase 1 (RIPK1) is critical in regulating necroptosis and inflammation, its precise contribution to sepsis‐induced lung injury remains poorly understood." (PMID 40953301, 2025). "ROC analysis demonstrated strong predictive performance for sepsis/septic shock using RIPK1 (AUC = 0.81), IL-18 (AUC = 0.71), and A20 (AUC = 0.71); conversely, caspase-8 was inversely associated with sepsis (AUC = 0.32)." (PMID 40722817, 2025). "Necroptosis contributes to sepsis-associated organ injury, and inhibiting key mediators like RIPK3 or RIPK1 alleviates systemic inflammation and organ damage in neonatal septic mice." (PMID 40832104, 2025). "We observed prominent necroptosis activation in sepsis—evidenced by elevated RIPK-1, IL-1β, and IL-18 levels and suppressed caspase-8 levels." (PMID 40722817, 2025).